ME1 (malic enzyme 1)
Diseases named in the same sentence as ME1 in open-access papers (continued):
Sharing a sentence is not in itself a finding about the gene and the disease.
hepatocellular carcinoma (7 papers, 2017 to 2026). A malignant tumor that arises from hepatocytes. "A significant upregulation of ME1 has been associated to aggressive hepatocellular carcinoma and to reduced overall survival and progression-free survival in this tumor type." (PMID 28352611, 2017). "We found that genetic inhibition of ME1 significantly suppressed colony numbers, migration, and invasion of hepatocellular carcinoma cells." (PMID 35924040, 2022). "KRAS mutations also upregulate ME1 expression in hepatocellular carcinoma (HCC), non-small-cell lung cancer (NSCLC), and colorectal cancer (CRC)." (PMID 39996805, 2025). "Finally, in vitro knockdown of ME1 suppressed proliferation, migration, and invasion of hepatocellular carcinoma cells." (PMID 35924040, 2022). "At the protein level, SIRT2 activates malic enzyme 1 (ME1) activity by deacetylating PGAM5, thereby promoting lipid synthesis and hepatocellular carcinoma (HCC) cell proliferation." (PMID 39930129, 2025).
pancreatic cancer (6 papers, 2017 to 2025). "Pancreatic cancer cells exhibited increased pyruvate carboxylation relative to fibroblasts, and this flux depended on both pyruvate carboxylase and malic enzyme 1 activity." (PMID 32648540, 2020). "PC and ME1 are each essential for pancreatic tumors in vivo, despite a possible redundancy in pyruvate carboxylation activity." (PMID 32648540, 2020). "Further evaluations of MDH inhibitors, together with the development of specific GOT1, ME1 inhibitors are expected as therapeutic options in pancreatic cancer." (PMID 29295482, 2017). "Other candidate background-specific trigenic interactions include the VDAC1/2/3 voltage-gated anion channel family and the ME1/2/3 malic enzyme family, two of which were previously shown to be synthetic lethal in pancreatic cancer under nutrient limiting conditions." (PMID 38678031, 2024). "GOT1 has been shown to be critical for maintaining mitochondrial oxidative phosphorylation as well as redox balance in pancreatic cancer cells through the production of NADPH, and ME1 is required for the generation of NADPH in this pathway." (PMID 38725581, 2023). "Taken together, these data argue that both PC and ME1 are important enzymes for PDAC cancer cells in tumors and can contribute to the pyruvate carboxylation activity observed in pancreatic cancer." (PMID 32648540, 2020). "Pancreatic cancer cells rely on a cytoplasmic glutaminolysis pathway producing pyruvate, which requires aspartate transaminase (GOT1, catalyzes aspartate to oxaloacetate), malate dehydrogenase (MDH1, catalyzes malate/oxaloacetate), and malate enzyme (ME1, catalyzes malate/pyruvate)." (PMID 29295482, 2017).
steatosis (6 papers, 2012 to 2023). Increased lipid within the cytoplasm of cells. "In addition, an association between increased ME1 gene expression and liver lipid accumulation has already been observed in different steatosis models, notably following high-fructose diet in mice." (PMID 36835354, 2023). "In the ME1-Tg group, 3 of 9 mouse livers displayed severe and diffuse macro- and micro-vesicular steatosis in areas surrounding the portal triad and hepatic vein, inflammatory foci, and intense Oil Red O staining." (PMID 25402228, 2014). "The degree of steatosis was positively correlated with mRNA expression of Pparg in livers of both genotypes; however, ME1-Tg mice displayed a stronger correlation." (PMID 25402228, 2014). "Nonetheless, MOD-1 mice had significant reductions in lipogenic enzyme gene expression and steatosis in the liver, suggesting direct or indirect ME1 action." (PMID 23056418, 2012). "Since liver-expressed Pparg and Me1 genes are both associated with hepatosteatosis, the reduced steatosis observed in our female obese MOD-1 mice is likely due, in part, to reduced Pparg and absent ME1 expression." (PMID 37047583, 2023).
diabetes (5 papers, 2010 to 2025). "Abnormal tubular lipid metabolism in diabetes is a risk factor for diabetic nephropathy, and ME1 is a risk factor for altered lipid metabolism." (PMID 39996805, 2025). "ME1 is involved in several benign diseases, including metabolic syndrome and diabetes." (PMID 39996805, 2025). "All of these lines of evidence support a diabetes-resistant phenotype in Me1−/− mice." (PMID 20463879, 2010). "Indeed, both male and female Me1−/− mice exhibited dramatically improved responses to an OGTT, as well as significantly lower plasma triglyceride levels (see Text S1 for further discussion of Me1 and diabetes)." (PMID 20463879, 2010). "Given that ME1, FFAR3, and FFAR2 are all candidate targets for anti-diabetes drugs, further elucidation of the networks/pathways that involve these molecules may prove valuable." (PMID 37047583, 2023).
colon cancer (4 papers, 2012 to 2025). "The present study is the first to evaluate the individual and combined effects of anti-obesogenic soy protein isolate intake and ME1 deficiency on systemic and tissue parameters that are known to affect propensity for colon cancer development." (PMID 23056418, 2012). "Here, we examined effects of soy protein diet and ME1 null mutation on serum concentrations of hormones implicated in colon cancer risk." (PMID 23056418, 2012). "ME1 was immunolocalized to specific cells of human normal colon and colon tumor tissue using a commercial tissue array." (PMID 30250042, 2018). "Consistently, we observe an increase in the expression of a key enzyme of glutaminolysis, malic enzyme 1, in advanced colon cancer." (PMID 26948869, 2016). "Our data identify roles for both ME1 and dietary protein type in mediating murine endocrine profile, body composition and adipose, liver and GI gene expression and suggest that attenuated ME1 expression/function may provide increased protection from colon cancer." (PMID 23056418, 2012). "Our results showed that the ME1 gene as well as SPI diet, significantly impact the endocrine profile of mice when challenged with obesogenic diet, and which potentially affects colon cancer propensity." (PMID 23056418, 2012). "We have reported that inclusion of soy protein isolate (SPI) in the diet lowered body fat content and colon tumor incidence of rats fed AIN-93G diet, while others have demonstrated SPI inhibition of rat hepatic ME1 expression." (PMID 23056418, 2012). "In their studies, single and combinational knockouts of G6PD, malic enzyme 1, and isocitrate dehydrogenase 1 identify the PPP as the largest contributor to NADPH production, indicating these other enzymes function as “backups” in colon cancer, with little impact on NADPH production." (PMID 40802750, 2025).
lung carcinoma (4 papers, 2018 to 2024). "In lung cancer patients with KRAS WT, except for MTHFD1, the expression levels of G6PD, IDH1, and ME1 were not correlated with the patient survival time." (PMID 38997257, 2024).
non-small cell lung carcinoma (4 papers, 2015 to 2025). A group of at least three distinct histological types of lung cancer, including non-small cell squamous cell carcinoma, adenocarcinoma, and large cell carcinoma. "Furthermore, analysis of the scRNA-seq data from the NSCLC_GSE127465 dataset identified 26 cell clusters and 12 cell types in non-small cell lung cancer tissues, with ME1 being enriched in both monocytes/macrophages and malignant cells." (PMID 40510340, 2025). "In non-small cell lung cancer, KRAS has a profound influence on glutamine metabolism through regulation of ME1 and GOT1, the high expression of which has been shown to correlate with poorer prognosis after radiotherapy." (PMID 27924922, 2016).
acute myeloid leukemia (3 papers, 2022 to 2025). Acute myeloid leukemia (AML) is a group of neoplasms arising from precursor cells committed to the myeloid cell-line differentiation. "In cytogenetically normal acute myeloid leukemia, ME1 activates the interleukin (IL)-6/Janus kinase 2 (JAK2)/signal transducer and activator of transcription 3 (STAT3) pathway, which correlates with poor prognosis." (PMID 39996805, 2025). "In acute myelocytic leukemia, melanoma, and papillary renal cell carcinoma, ME1 overexpression is similarly correlated with poor prognosis." (PMID 39996805, 2025). "ME1 overexpression induces radioresistance in head-and-neck SCC and NSCLC and has also been reported in acute myelocytic leukemia, NSCLC, HCC, and prostate cancer." (PMID 39996805, 2025).
Insulin resistance (3 papers, 2014 to 2023). Increased resistance towards insulin, that is, diminished effectiveness of insulin in reducing blood glucose levels. "We suggest that ME1 mediates tissue insulin resistance, in part, by affecting tissue steady-state levels of IRS proteins." (PMID 25402228, 2014). "In addition, the strong associations of ME1 with leptin, PPAR-γ, and TNF-α support significant role(s) for hepatic ME1 in predisposition for insulin resistance and type II diabetes mellitus." (PMID 37047583, 2023). "Notably, the enhanced liver IRS1 activation concomitant with increased blood glucose in ME1-Tg mice suggests the onset/development of systemic insulin resistance." (PMID 25402228, 2014). "The intestinal ME1-directed liver phenotype was accompanied by increased hepatic IRS1 activation in Tg mice, consistent with the development of whole body insulin resistance and with increased mRNA expression of Protein Kinase C-ε, known to be associated with hepatic insulin resistance." (PMID 25402228, 2014).
Oral Squamous Cell Carcinomas (3 papers, 2020 to 2025). "We previously demonstrated the correlation between increased ME1 expression and malignancy in oral squamous cell carcinomas, particularly invasiveness due to epithelial–mesenchymal transition at the cancer front." (PMID 39859378, 2025). "In this study, we investigated the role of ME1 in tumor budding in oral squamous cell carcinoma (OSCC), in which we had found a significant role for ME1 in tumor progression and EMT." (PMID 32998265, 2020). "Malic enzyme 1 (ME1) promotes the Warburg effect in cancer cells and induces epithelial–mesenchymal transition (EMT) in oral squamous cell carcinoma (OSCC)." (PMID 32998265, 2020).
adenoma (2 papers, 2018 to 2025). A neoplasm arising from the epithelium. "ME1 overexpression in APCMIN/+ mice increases adenomas due to activation of the Wnt/β-catenin pathway and increases expression of KLF9." (PMID 39996805, 2025). "Male ApcMin/+/ME1-Tg mice exhibited greater small intestine crypt depth and villus length in non-adenoma regions, correspondent with increased KLF9 protein abundance in crypts and lamina propria." (PMID 30250042, 2018). "Both adenoma number and area were significantly greater (P = 0.032 and P = 0.004, respectively) for ilea of male ApcMin/+/ME1-Tg mice compared to male ApcMin/+ mice." (PMID 30250042, 2018). "Evaluation of apoptosis by TUNEL revealed tendencies for decreased staining in the villi and adenomas of ApcMin/+/ME1-Tg compared to ApcMin/+ mice." (PMID 30250042, 2018). "ApcMin/+/ME1-Tg mice displayed significantly greater numbers of adenomas that were less than 1 mm in diameter in the duodenum (P = 0.011), jejunum (P = 0.014), and ileum (P = 0.040) when compared to male ApcMin/+ mice." (PMID 30250042, 2018). "ME1 protein levels were significantly greater within gut epithelium and adenomas of male ApcMin/+/ME1-Tg than ApcMin/+ mice." (PMID 30250042, 2018). "Sixteen-week-old male mouse progeny were used to quantify Me1 RNA abundance and adenoma burden in the small and large intestines." (PMID 30250042, 2018). "Male ApcMin/+/ME1-Tg mice had larger and greater numbers of adenomas in the small intestine (jejunum and ileum) than male ApcMin/+ mice." (PMID 30250042, 2018). "ApcMin/+/ME1-Tg mice exhibited greater amounts of ME1 protein in adenomas when compared to those of ApcMin/+." (PMID 30250042, 2018). "We observed increases in: a) adenoma number and size distribution, b) ME1 abundance within adenomas, and c) crypt depth and villus height, in the non-adenoma (transitional) mucosa with Me1 overexpression in the background of Apc haplo-insufficiency." (PMID 30250042, 2018). "However, the adenoma borders of ApcMin/+/ME1-Tg mice displayed significantly greater (P = 0.042) ME1 staining than those of ApcMin/+ mice." (PMID 30250042, 2018). "Interestingly, the borders of adenomas exhibited significantly greater ME1 staining than the corresponding inner regions irrespective of genotype." (PMID 30250042, 2018). "The greater numbers of small adenomas and the larger adenoma sizes, respectively within the small intestine of ApcMin/+/ME1-Tg mice, coincident with increased ME1 expression, are suggestive of ME1 promotion of the initial step(s) of adenoma formation and of ME1 participation in tumor progression." (PMID 30250042, 2018). "Finally, we showed that ME1 is abundantly expressed within epithelial-like regions of human colon adenocarcinoma akin to what was observed in the adenoma borders in ApcMin/+/ME1-Tg mice." (PMID 30250042, 2018). "Moreover, the significant elevation in ME1 abundance within the adenoma borders is consistent with previously reported increases in lipid content in the epithelial-like adenoma borders of ApcMin/+ mice." (PMID 30250042, 2018). "Interestingly, the number of adenomas between 3 mm and 4 mm in diameter was significantly greater (P = 0.034) in the colons of male ApcMin/+/ME1-Tg mice compared to ApcMin/+ mice." (PMID 30250042, 2018). "While we found no quantitative effects of the Me1 transgene on this pattern, there was a significant increase in the number of goblet cells in the adenoma-associated villi when compared to normal villi." (PMID 30250042, 2018). "Animal studies have demonstrated tumor growth in mouse models and increased adenocarcinomas and adenomas in APCMIN/+- and ME1-overexpressing mice." (PMID 39996805, 2025).
clear cell renal cell carcinoma (2 papers, 2022 to 2023). "CircME1 bound to U1 snRNP and increased the transcription of its parental gene ME1, thus promoting aerobic glycolysis and sunitinib resistance of clear cell renal cell carcinoma." (PMID 37173608, 2023).
liver cancer (2 papers, 2022 to 2024). An epithelial or non-epithelial malignant neoplasm that arises from the liver. "PGAM5, in turn, dephosphorylates and activates malic enzyme 1 (ME1), leading to lipid accumulation and liver cancer cell proliferation." (PMID 39063217, 2024). "IN HPA database, immunohistochemistry showed that the expressions of APEX1, ME1, S100A10 and ACACA in liver cancer tissues were significantly higher than those in paired normal liver tissues, while ADH1C, and CYP2C9 were expressed at low levels in tumor tissues compared with adjacent normal tissues." (PMID 36456877, 2022). "Interestingly, in liver cancer, PGAM5 dephosphorylates the total level of ME1 without altering the dephosphorylation of S336 ME1." (PMID 39063217, 2024).
mesothelioma (2 papers, 2019 to 2025). A usually malignant and aggressive neoplasm of the mesothelium which is often associated with exposure to asbestos. "In combination with AUA1—an antibody which recognizes a human cell surface antigen on epithelial cells —ME1 and ME2 recognized both normal mesothelial cells and mesothelioma." (PMID 30965570, 2019). "ME1 and ME2: The monoclonal antibodies ME1 and ME2, which were initially generated by immunizing mice with the mesothelioma cell line SPC111, have been used to study human cultured mesothelial cells and ovarian tumor cells." (PMID 30965570, 2019).
ovarian carcinoma (2 papers, 2020 to 2025). A malignant neoplasm originating from the surface ovarian epithelium. "In ovarian cancer, the top 50 positively and negatively correlated genes associated with ME1 were further analyzed and presented in a heat map." (PMID 40510340, 2025). "The findings indicated that ME1 was expressed at lower levels in human ovarian cancer cell lines compared to normal ovarian cells." (PMID 40510340, 2025). "ME1, a metabolic-related factor, has the potential to serve as a biomarker for tumor progression and immune infiltration, particularly in ovarian cancer." (PMID 40510340, 2025). "To further investigate the critical role of ME1 in OV, we transduced the human ovarian cancer cell lines A2780 and OVCAR3 with a ME1-overexpressing lentiviral and a negative control vector." (PMID 40510340, 2025). "To elucidate the biological functions of ME1 in ovarian cancer, we conducted gene enrichment analysis using the LinkedOmics database." (PMID 40510340, 2025). "We initially employed WB and qRT-PCR to assess the baseline expression of ME1 in normal ovarian cells as well as in ovarian cancer cell lines A2780 and OVCAR3, which aligns with the findings from our biological information analysis." (PMID 40510340, 2025). "We identified two effective ME1 siRNA primer sequences and assessed the knockdown efficiency of ME1 through qRT-PCR and WB in human ovarian cancer cell lines A2780 and OVCAR3." (PMID 40510340, 2025). "In vitro research results demonstrated that in ovarian cancer cell lines, the knockdown of ME1 inhibited the proliferation and migration of tumor cells." (PMID 40510340, 2025). "Analysis of the scRNA-seq data from the OV_GSE115007 dataset identified 12 cell clusters and 3 cell types within ovarian cancer tissues, with ME1 exhibiting enrichment primarily in monocytes/macrophages." (PMID 40510340, 2025). "Small interfering RNA and chronic viruses were utilized to downregulate and upregulate ME1 expression in two ovarian cancer cell lines, respectively, to conduct experiments on cell proliferation and migration." (PMID 40510340, 2025). "We categorized the ME1 expression values of ovarian cancer patients into high and low expression groups based on the median." (PMID 40510340, 2025). "The cell experiments conducted in this study provide direct evidence elucidating the role of ME1 in ovarian cancer cell lines." (PMID 40510340, 2025). "A metabolic pathway was the most significant pathway enriched by GGPS1, ME1, DSE, NTPCR, PPOX, and PC.ME1 and DSE have been reported to be associated with the development of ovarian cancer in previous studies." (PMID 33177242, 2020). "Among the metabolic pathway-related genes, ME1 and DSE have been reported to be associated with ovarian cancer." (PMID 33177242, 2020). "Although the importance of pan-cancer analysis in understanding tumorigenesis and progression is self-evident, research on the role of ME1 across various cancers is notably insufficient, particularly regarding its role in ovarian cancer, which remains largely unexplored." (PMID 40510340, 2025). "Therefore, our objective is to analyze the potential functions of ME1 in pan-cancer, with a particular focus on its role in ovarian cancer." (PMID 40510340, 2025). "Simultaneously, we are conducting experimental validation of cellular functions in ovarian cancer cell lines to further elucidate the role of ME1 in the development and progression of ovarian cancer, with the hope of providing new insights for its diagnosis and treatment." (PMID 40510340, 2025). "Additionally, we observed that reducing ME1 expression led to a decrease in the proliferation and migration capabilities of ovarian cancer cells." (PMID 40510340, 2025). "Furthermore, we confirmed that high expression levels of ME1 promote the proliferation and migration of ovarian cancer cells." (PMID 40510340, 2025).
ovarian carcinoma (continued). "The results indicate that ME1, as a metabolic hub, may drive immune escape in ovarian cancer through multidimensional interactions involving redox balance, secretory pathways, and cytokine signaling." (PMID 40510340, 2025). "We assessed the basal expression levels of ME1 in normal ovarian cells (IOSE80) and in human ovarian cancer cell lines (A2780, and OVCAR3) using Western blotting (WB) to analyze protein expression levels." (PMID 40510340, 2025).